Y_RNA (Y RNA )
Gene: Miscellaneous RNA gene on chromosome 5 (139,554,900 to 139,555,001, reverse strand). Ensembl gene ENSG00000207020.
Homologues: Orthologues: chimpanzee Y_RNA (99% identical), macaque Y_RNA (94% identical). Paralogues in human: Y_RNA (85% identical), RNY3 (84% identical), Y_RNA (84% identical), RNY3P1 (83% identical), Y_RNA (83% identical), Y_RNA (82% identical), Y_RNA (81% identical), RNY3P7 (80% identical), Y_RNA (80% identical), RNY3P11 (79% identical), RNY3P14 (79% identical), Y_RNA (79% identical), and 91 more.